LEP (leptin)
Diseases named in the same sentence as LEP in open-access papers (continued):
Sharing a sentence is not in itself a finding about the gene and the disease.
breast cancer (continued). "In this work we aim to assess how models based on data which can be collected in routine blood analyses - notably, Glucose, Insulin, HOMA, Leptin, Adiponectin, Resistin, MCP-1, Age and Body Mass Index (BMI) - may be used to predict the presence of breast cancer." (PMID 29301500, 2018). "Since ADIPO and LEP activate antagonistic intracellular signaling pathways, it appears that the ratio of ADIPO:LEP may be a more reliable predictor of cancer incidence and outcome in breast cancer patients." (PMID 28873415, 2017). "Moreover, inhibition of AMPK signaling inhibited leptin-induced FoxO3A expression, clearly demonstrating that leptin-induced FoxO3A expression is mediated by AMPK signaling-dependent mechanism in MCF-7 breast cancer cells." (PMID 29312618, 2017). "Thus, Leptin and SAHA affect G0/G1-S-phase transition of the breast cancer cell cycle." (PMID 27926517, 2017). "Therefore, our data indicate that Leptin and SAHA may be related to the activation of apoptosis pathway in breast cancer cells, especially induced by the endogenous mitochondrial apoptosis pathway." (PMID 27926517, 2017). "Thus, PA serves as a means to alter ADIPO:LEP ratio and subsequent tumor growth microenvironment in obese breast cancer patients, regardless of their menopausal status." (PMID 28676553, 2017). "Here, we investigated how leptin, as a mediator of tumor-stromal interactions, may affect BCSC activity using patient-derived samples (n = 16) and breast cancer cell lines, and determined the potential benefit of targeting leptin signaling in these model systems." (PMID 26556856, 2016). "The data in the current study suggest that leptin may up-regulate ObR to activate the P38/MAPK and MAPK/ERK 1/2 signaling pathways, which in turn stimulate IL-8 promoter and IL-8 production in M2 macrophages, consequently promoting breast cancer progression." (PMID 27588409, 2016). "As clinical implications, these data suggest that targeting leptin/leptin receptor signaling generated in the microenvironment may be useful for BCSC eradication and eventually to prevent recurrence and metastasis in patients with breast carcinoma." (PMID 26556856, 2016). "We showed that ex vivo isolated adipocytes from obese adipose tissue are the major source of leptin production in our tumor model: we demonstrated that E0771 mammary tumor cells, in contrast to the majority of mammary/breast tumor cell lines, do not express leptin." (PMID 25599228, 2015). "To assess the in vivo role of leptin in tumor progression and macrophage recruitment to the mammary tumor microenvironment in DIO mice fed 33%HFD, we analyzed whether specifically blocking leptin signaling in mice with different body weights had any effect in tumor progression." (PMID 25599228, 2015). "For example, in a hospital-based case-control study of 74 female breast cancer patients and 76 controls, HMW was shown to be strongly and inversely associated with breast cancer risk, independent of classical risk factors such as leptin and the IGF-1 system." (PMID 26070203, 2015). "Given our in vitro and in vivo results showing that HNK inhibits Wnt1-β-catenin axis and its important role in oncogenic function of leptin, we decided to examine whether inhibition of Wnt1-β-catenin axis is integral for HNK-mediated inhibition of breast cancer growth, invasion and migration." (PMID 26036628, 2015). "Importantly, to our knowledge, leptin-mediated activation of SFKs has not been previously reported in breast cancer and here we provide the first evidence of leptin-mediated SFKs phosphorylation at Tyr 416 in ER-negative breast cancer cell lines." (PMID 25482303, 2014). "The SK-BR-3 breast cancer cells exhibited a concentration-dependent increase in proliferation with physiological leptin concentrations (<100 ng/ml), but no further increase in proliferation at high leptin concentrations (>100 ng/ml) was observed." (PMID 24959279, 2014).
breast cancer (continued). "However, previous studies investigating the effect of leptin treatment on proliferation in breast cancer cells did not or only marginally exceeded maximal physiological leptin concentrations of 100 ng/ml." (PMID 24959279, 2014). "Therefore, Notch, IL-1 and leptin crosstalk outcome (NILCO) could be essential for the integration of leptin’s proangiogenic, pro-inflammatory and proliferative actions in breast cancer." (PMID 24716804, 2014). "In MDA-MB-231 breast cancer cells, proliferation did not change significantly after 24 h of treatment with leptin and decreased significantly by 11% (P=0.023) and 26% (P<0.001) after 48 h of treatment with 400 and 800 ng/ml (P<0.001) of leptin, respectively, compared with the untreated control." (PMID 24959279, 2014). "Remarkably, the inhibition of leptin signaling via leptin peptide receptor antagonist 2 (LPrA2) significantly reduced VEGF/VEGFR2 expression and angiogenesis in human xenografts, estrogen responsive, MCF-7 and non-responsive, MDA-MB231-triple negative breast cancer cells, and mouse mammary tumors." (PMID 24202338, 2013). "LEP has been reported as biomarkers in breast cancer, though not in lung cancer." (PMID 24369052, 2013). "Though not significant, the leptin level was found to be higher in breast cancer patients of group E. Therefore, it might be possible to distinguish breast cancer and breast benign diseases by evaluating leptin level." (PMID 23826274, 2013). "We do not have information on family history of breast cancer, parity, or measures of other hormones such as insulin or leptin that might influence endogenous sex hormone concentrations." (PMID 23113944, 2012). "However, the molecular mechanisms of leptin pro-angiogenic actions in breast cancer are still not fully understood." (PMID 21731759, 2011). "Some studies support the hypothesis that the absence of leptin signaling diminishes mammary tumor growth in mice." (PMID 21338489, 2011). "However, the interaction between HER2 and the leptin system has not been well explored in breast cancer." (PMID 18945363, 2008). "However, the existence of functional leptin/HER2 interactions in human breast cancer has not been explored." (PMID 18945363, 2008). "Moreover, leptin and AQP1 may be potential biomarkers in VM-related breast cancer." (PMID 38791252, 2024). "Additionally, the treatment of M2 macrophages with leptin activates the IL-8 promotor through the p38/MAPK and MAPK/ERK1/2 pathways leading to increased IL-8 secretion resulting in enhanced tumor growth in vivo and increased migration and invasiveness in breast cancer cell lines." (PMID 39439572, 2024). "Furthermore, leptin was reported to stimulate the secretion of TGFβ, which leads to the activation of SMAD family member 2 (Smad2), Smad3, and Smad4 transcription factors, the repression of cadherin 1 (CDH1) coding for E-cadherin, and an increased CSC phenotype in breast cancer cells." (PMID 36010901, 2022). "Moreover, both the CPT1 inhibitor perhexiline and an anti-leptin antibody are able to mitigate tumor growth by upregulating cytokine release by CD8+ T cells, indicating that targeting the leptin-PD-1-STAT3-FAO pathway represents a new direction in treating breast cancer." (PMID 39872079, 2022). "Using co-injections of breast cancer cells and adipocytes or pre-adipocytes into nude mice, BMP9 was found to inhibit the growth and metastasis of breast cancer cells, which may be in part related to their interaction with pre-adipocytes or adipocytes via leptin signaling." (PMID 33498240, 2021). "Interestingly, while previous studies have demonstrated that leptin induces growth of breast cancer cells in an autophagy‐dependent manner, whether autophagy contributes to leptin‐induced metabolic alterations has never been assessed." (PMID 33226729, 2021).
breast cancer (continued). "Indeed, while elevated body weight is believed to promote tumorigenesis, obese mice with deficits in the expression of leptin or leptin receptors failed to develop mammary tumors in a mouse mammary tumor virus enhancer/promoter-transforming growth factor alpha transgenic mouse model." (PMID 33535537, 2021). "However, leptin did not upregulate leptin receptor expression in breast cancer cells." (PMID 32836215, 2020). "However, the effects of leptin on bone metastasis in breast cancer are not fully understood." (PMID 32836215, 2020). "In vivo leptin signaling inhibition reduced Notch and target expression (NICD1, NICD4, Notch3, JAG1 and survivin), suggesting that leptin-Notch crosstalk could be involved in the reported higher incidence, aggressiveness and poor prognosis of breast cancer in obese patients." (PMID 30004402, 2018). "However, leptin expression in mammary tumor tissue is not characteristic of blood leptin levels, but could be a result of the paracrine mechanism." (PMID 29121911, 2017). "Furthermore, studies have shown the blockade of IL-1 receptor partially abrogated leptin-mediated increase of both VEGF and VEGFR2 protein and mRNA, strongly suggest that leptin pro-angiogenic signature in breast cancer could partially be mediated by IL-1 signaling." (PMID 27472371, 2016). "However, an experimental study showed that leptin may induce proliferative response in breast cancer cells but not in the normal breast cells." (PMID 27293305, 2016). "Thus, leptin’s actual concentrations in the tumor microenvironment of the E0771 obese mammary tumor model may not be as high as the ones which experimentally downregulated its receptor in macrophages." (PMID 25599228, 2015). "Also, numerous breast cancer cell lines such as MCF-7 and T47D could express leptin and ObR." (PMID 25866478, 2014). "Similarly to leptin, an oncogenic lipid kinase SK1 was shown to be overexpressed in human breast tumours and linked with poor prognosis, yet the mechanism of its upregulation in breast cancer was not clear." (PMID 25482303, 2014). "However, no studies have been performed on the leptin regulation of IL-1 in breast cancer." (PMID 21139583, 2011). "Furthermore, it is a lack of information on whether high levels of leptin in obese patients parallel the levels of IL-1 in breast cancer." (PMID 21139583, 2011). "Therefore, leptin-mediated induction of ERα through Notch signaling might represent a negative feed-back loop for Notch expression in breast cancer." (PMID 21731759, 2011). "Moreover, present findings show for the first time that leptin and Notch collaborate for the induction of cell proliferation/migration and that a complex signaling network between Notch, IL-1 and leptin (NILCO) is required for the upregulation of VEGF/VEGFR-2 in breast cancer." (PMID 21731759, 2011). "Here we have investigated the effects of Acrp30 and ERα in the absence of other factors such as oestradiol, leptin or serum on a number of breast cancer cell lines to clarify the role of Acrp30 on cell growth and how ERα without significant doses of high-affinity ligands may affect this role." (PMID 18182989, 2008). "However, the clinical studies on circulating leptin levels and breast cancer are not conclusive." (PMID 21566743, 2008). "Importantly, previous works have demonstrated that CYP1B1 is overexpressed in breast cancer cells and that leptin upregulates CYP1B1 mRNA and protein expression in breast cancer, thus suggesting that increase in CYP1B1 expression may be one of the mechanisms for the pro‐tumoral activity of leptin." (PMID 39806854, 2025). "This is consistent with other research which demonstrated that while leptin increases invasive capability of MCF-7 and SKBR3 breast cancer cells, it does not influence protein levels of OB-R." (PMID 39609706, 2024).
breast cancer (continued). "Thus, therapies that jointly target leptin signaling alongside anti-VEGF therapy may help breast cancer patients – many (but not all) of whom are obese – in which conventional anti-VEGF combination therapy is less effective, such as in Her2-negative breast cancer." (PMID 39439572, 2024). "In addition, Leptin was significantly lower in the peripheral blood of the observation group (breast cancer patients who developed fatigue after chemotherapy) compared to the control group (breast cancer patients who did not develop fatigue after chemotherapy)." (PMID 37542585, 2023). "In both ERα-positive and ERα-negative human breast cancer cells, LDFI inhibited leptin-induced proliferation, motility, and signaling activation." (PMID 37626871, 2023). "While CTLA-4 is a protein related to the inflammatory response that is increased in breast cancer patients, contributing to immune downregulation, TNF-α is a pro-inflammatory cytokine that induces apoptosis promoted by the absence of leptin." (PMID 33644151, 2021). "In a later study, the effect of mAb, 9F8, on leptin-induced cell viability and proliferation of ERα-positive (MCF7) and ERα-negative (MDA-MB 231) human breast cancer cell lines was analysed." (PMID 34356668, 2021). "The LDFI peptide acted as a full leptin antagonist by inhibiting the leptin-induced growth and migration in both ERα-positive (MCF-7) and ERα-negative (SKBR3) breast cancer cells without interfering with cell proliferation in the absence of leptin." (PMID 34356668, 2021). "Finally, our results demonstrated that cats with low ObR-expressing mammary tumors had higher serum ObR levels, indicating a negative feedback between tumor microenvironment and serum, probably due to a shedding mechanism that leads to a reduction of serum leptin levels." (PMID 33644151, 2021). "The peptide LDFI abolished the leptin-induced anchorage-dependent and -independent growth as well as the migration of ERα-positive (MCF-7) and -negative (SKBR3) breast cancer cells." (PMID 25721149, 2015). "First, we tested the biological activity of the peptide LDFI on anchorage-dependent cell proliferation using as experimental models ObR-positive and leptin-sensitive MCF-7 (ERα-positive) and SKBR3 (ERα-negative) breast cancer cells." (PMID 25721149, 2015). "Here we show that NILCO components (Notch1, Notch4, JAG1, DLL4, leptin, OB-R, IL-1R tI) and target molecules (VEGF and VEGFR2) were co-expressed in breast cancer tissues, irrespective of ER, PR and, HER2 statuses." (PMID 24716804, 2014). "Such phenotypic differences were also reproduced upon leptin treatment in ERα-negative MDA-MB-231 and in MDA-MB-468 breast cancer cells." (PMID 25505738, 2014). "Until now no direct links between leptin-mediated signalling and SK1 in breast cancer have been documented." (PMID 25482303, 2014). "When we stratified the patients according to the menopause status (190 pre-menopausal and 118 post-menopausal) no significant changes in the LEP and LEPR genotype distributions were seen in breast carcinoma subgroups (data not shown)." (PMID 16504019, 2006). "Novel therapeutic strategies, such as LEP or LEPR antagonist, are not currently under development, although they would represent a promising step toward a more personalized treatment approach for breast cancer patients." (PMID 36291602, 2022). "Furthermore, leptin has a growth-stimulating effect on both estrogen receptor–positive breast cancer (MCF7, T47D, MDAMB361) and estrogen receptor–negative breast cancer (MDAMB231, SKBR3) cell lines." (PMID 34868066, 2021). "According to our results, we suggest that overweight breast cancer patients have a better prognosis regardless of the YKL-40, leptin, and adiponectin levels since we estimated an approximately three-fold increased risk of disease recurrence or death for normal-weight versus obese women." (PMID 32512860, 2020).
breast cancer (continued). "Thus, our results suggest that a non-obese phenotype with high leptin and YKL-40 and low adiponectin levels in breast cancer leads to cancer cell migration and invasion to promote metastasis and reduced survival." (PMID 32512860, 2020). "Leptin and LEPR are overexpressed in breast cancer as compared to non-cancer mammary epithelium." (PMID 31380268, 2019). "Finally, evidence proved that leptin, but not OB3, increased blood serum follicle-stimulating hormone (FSH) which was proven to play important roles in the initiation and proliferation of breast cancer and gynecological cancers." (PMID 28750624, 2017).